CD4 (CD4 molecule)
Diseases named in the same sentence as CD4 in open-access papers (continued):
Sharing a sentence is not in itself a finding about the gene and the disease.
colitis (continued). "The histological analysis of intestinal inflammation showed severe colitis in host mice that had received wildtype or Stim2‐deficient CD4+ T cells, whereas inflammation was partially reduced or absent following transfer of Orai1‐deficient and Stim1‐deficient CD4+ T cells, respectively." (PMID 35919953, 2022). "As the pathogenesis of disease In the T cell transfer model of colitis is largely associated with unrestricted Th1/Th17 CD4+ T cell responses in the absence of Tregs, we next decided to investigate what effect IL-36 signalling has on CD4+ T cell responses in vivo, in this setting." (PMID 35177818, 2022). "We also showed that this sequence can be disrupted - and colitis severity greatly attenuated - either by restoring gut microbiome homeostasis (via replacement of gut reg3g), or by directly attenuating the pathogenic function of the colitogenic CD4+ T cell population (via p40 inhibition)." (PMID 36704549, 2022). "Thus, in future studies, it will be informative to test the hypothesis that DN iNKT cells are critical for preventing IFNγ-driven colitis pathogenesis by suppressing pathogenic Foxp3−CD25+CD4+ T cell differentiation." (PMID 36499642, 2022). "In addition, imbalanced CD4+ T cells have been reported as predisposing factors for colitis." (PMID 34456974, 2021). "Moreover, NFATc2 deficiency suppresses CD4+ T cell-mediated colitis in mice." (PMID 33251043, 2020). "Thus, mRNA expression of Notch1 and Hes1 was examined in the CD4+ T cells from patients with different H. pylori–associated gastrointestinal tract inflammation including gastritis, duodenal ulcer, gastritis with duodenal ulcer, and gastritis with colitis." (PMID 33224898, 2020). "However, an important question remaining to be answered is whether the Asc−/− Tregs are also potent enough to prevent the onset of exacerbated colitis caused by adoptive transfer Asc−/− naïve CD4+ T cells into Rag-1−/− recipients." (PMID 31379813, 2019). "The passive transfer of naïve cytochrome p450 family 26 subfamily b1-deficient (Cyp26b1−/−) mice CD4 T cells into recombination-activating gene 1-deficient (Rag1−/−) mice resulted in a significantly reduced disease state in a model of T cell-dependent colitis." (PMID 30158832, 2018). "To determine whether the loss of NLRP3 inflammasome function and the resulting increased susceptibility to experimental colitis were driven by changes in T cell phenotype, we assessed the expression of IL-10 in CD4+ and CD8+ T cell populations isolated from the colonic LP." (PMID 27610005, 2016). "Importantly, these resident BM CD4+ memory T cells are closely associated with IL-7-producing stromal cells, and they cannot induce colitis when transferred into IL-7−/− × Rag1−/− mice, suggesting that IL-7 plays an essential role in their maintenance or survival in the BM." (PMID 26734007, 2015). "Furthermore, we adoptively transferred Rap1-deficient CD4+ pathogenic T cells into the radiated normal mice, and investigated whether the expression of T567E ezrin reduced the development of colitis." (PMID 26634692, 2015). "While IL-27Rα+ lymphopenic mice that receive naïve CD4 T cells develop chronic colitis associated with colitogenic Th1 and Th17 type effector cell generation, lymphopenic mice deficient in IL-27Rα are completely protected from the colitis after the T cell transfer." (PMID 25126585, 2014). "Moreover, administration of exogenous IL-23 in RAG mice reconstituted with naïve CD4+ T-cells caused a more severe colitis that was associated with enhanced production of IL-6 and IL-17 and preventable by treatment of mice with a blocking IL-6 or IL-17 antibody." (PMID 19503799, 2009). "In a mouse model of colitis, researchers found that ERα deletion in CD4+ T cells led to decreased colitis severity, accompanied by fewer IFNy+ and interleukin (IL)‐17A+ proinflammatory CD4+ T cells and increased CD4+ T regulatory cells." (PMID 41580387, 2026).
colitis (continued). "After five weeks, Rag1−/− mice reconstituted with CD4+ CD45Rbhi T cells developed severe colitis, which was inhibited by the co‐transfer of WT Tregs." (PMID 41178490, 2026). "Here, we show that IL-37 alleviates colitis by reducing global m6A levels and reshaping CD4+ T-cell metabolism." (PMID 42263254, 2026). "Consistent with impaired central tolerance, we detected high serum titers of autoantibodies against several tissues, increased frequency of effector CD4+ T cells and Tregs, and symptoms of colitis." (PMID 41481333, 2026). "For example, Tim4+CD4+ macrophages in the colon of colitis mice showed immunosuppressive capacity to inhibit T cells proliferation and induce T cells apoptosis." (PMID 41362741, 2026). "In a chronic IBD model, SpNWS-enabled SNS mitigated colitis symptoms, preserved mucosal structure and rebalanced CD4+ T cell subsets." (PMID 41585589, 2026). "iTregs derived from Tdrd3fl/fl/Foxp3YFP-Cre mice also exhibited impaired suppressive function, both in vitro, in inhibiting CD4+ T cell proliferation, and in vivo, in an adoptive transfer model of colitis." (PMID 41576154, 2026). "A naïve CD4+ T cell transfer colitis model was used to evaluate the suppressive function of iTregs in the presence or absence of CD8+ T cells, while an autoimmune arthritis model was employed to assess therapeutic efficacy." (PMID 41736071, 2026). "To confirm the regulatory effect of SHP2 on Treg differentiation, we established an adoptive transfer colitis model by transferring CD4+CD25−CD45RBhigh T cells into Rag1−/− recipient mice." (PMID 40757098, 2025). "Recent experimental evidence suggests that the differentiation of naïve CD4+ T cells towards Tregs is inhibited in DSS‐induced colitis." (PMID 40842289, 2025). "Compared to the Rag1−/− mice receiving CD4+CD25−CD45RBhigh T cells from SHP2f/f donors, recipients of cells from CD4‐Cre;SHP2f/f mice exhibited attenuated colitis severity, as evidenced by reduced weight loss and diminished colon shortening." (PMID 40757098, 2025). "RAP1 has been shown to promote the differentiation of naive CD4+ T cells into Tregs while inhibiting their differentiation into Th17 cells in spontaneous colitis, indicating its potential involvement in Treg regulation." (PMID 40892462, 2025). "Regarding T cells in gut inflammation, colitis involved excess IL-12 and IFN-γ (“Th1” cytokines) and pathogenic CD8 cells, but CD4 T cells were protective in this model." (PMID 40938333, 2025). "To delve deeper into the molecular mechanism through which Atg7 enhances colitis and controls the CD4+ T cells functions, we obtained naive CD4+ T cells derived from the spleen of Atg7ΔCD4 and Atg7fl/fl mice." (PMID 40887825, 2025). "Our further analysis revealed that the deficiency of NAT10 led to a disruption of T cell development at steady state, and identified a pivotal role for NAT10 in preserving the pathogenicity of naïve CD4+ T cells to induce adoptive transfer colitis." (PMID 40038243, 2025). "Compared to colitis rats that received MLB cells from the control group, those that received MLB cells from the colitis group exhibited higher levels of CD3+CD4+ T cells, while they had little effect on CD3+CD8+ T cells." (PMID 40331987, 2025). "Regarding the construction of IBD models, one study used the Trinitrobenzene Sulfonic Acid (TNBS)-induced model, one study used the Transfer Colitis Model (CD4+ CD62L + T cell transfer-induced), and the rest of the study used the DSS-induced model." (PMID 40395731, 2025). "Time-restricted feeding (TRF) has been discovered to decrease intestinal inflammation in DSS-induced colitis models by increasing the number of CD4+CD25+ T cells and decreasing the fraction of CD4+ T cells in peripheral blood and mesenteric lymph nodes." (PMID 41476956, 2025). "The results revealed that SHP2‐deficient CD4+CD25−CD45RBhigh T cells exhibited weakened pathogenicity, manifested as alleviated colitis symptoms in recipient mice." (PMID 40757098, 2025).
colitis (continued). "Etv1 deficiency impairs CD4+ T cell activation, proliferation, and T helper 17 (Th17) cell differentiation, thereby ameliorating TNBS-induced colitis." (PMID 41347630, 2025). "Here, we revealed that high fructose consumption exacerbates dextran sulfate sodium salt (DSS)-induced colitis and CD4+CD25−CD45RBhi T cell transfer-induced colitis by promoting the generation of T helper-1 (Th1) and Th17 cells." (PMID 40854873, 2025). "Another study found that the number of CD4+TRM cells in DSS-induced colitis mice was significantly higher than that in normal mice, and the number of CD4+CD69+CD103-TRM cells was positively correlated with the disease activity index." (PMID 40529369, 2025). "Then, we examined the differentiation of CD4+ T cells in the LP of mice with colitis by flow cytometry and found that the number of TH17 cells was significantly upregulated by WT-EVs stimulation but downregulated by ΔPMA1-EVs stimulation." (PMID 39886799, 2025). "As observed in the EAE model, we also identified CD4+Notch2+ T cells in the lamina propria region of the colitis model mice; this population also expressed the TCR." (PMID 40702356, 2025). "Treatment with GSSSG significantly ameliorated body weight reduction and histological colitis induced by Cars2+/- naïve CD4+ T cell transfer." (PMID 40303402, 2025). "To seek this possibility, we used a mouse model of colitis where naïve CD4+ T cells are transferred into lymphodeficient mice." (PMID 40303402, 2025). "Tfam deficiency, which reduces the synthesis and stabilization of mitochondrial DNA (mtDNA), reduces peripheral T cells but increases IFN-γ- and TNF-α-producing effector CD4 T cells, exacerbating age-associated multimorbidity and DSS-induced colitis." (PMID 41451235, 2025). "Increased NO produced by MDSCs was shown to exacerbate colitis and promote death of Il-10−/− mice with colitis, though those MDSCs remained suppressive to CD4+ T cells." (PMID 40244120, 2025). "As a consequence, we studied the role and mechanism of Atg7 in controlling CD4+ T cell differentiation as well as sustaining the gut environment balance in colitis mice." (PMID 40887825, 2025). "In contrast, another study reported that Tregs undergo accelerated senescence compared to conventional CD4+ T cells due to defective antioxidant responses, rendering them unable to protect mice from CD4+ T cell-induced colitis." (PMID 40410784, 2025). "For instance, in the context of IBD, Blimp-1-mediated IL-10 production by CD4+ T cells has been demonstrated to suppress colitis." (PMID 40375985, 2025). "DSS-induced colitis mice exhibited a notably increased number of CD4+ TRM cells in vivo compared with that in control mice, and these levels markedly decreased after treatment." (PMID 40529369, 2025). "In the model of adoptive transfer colitis, the SHP2‐deficient CD4+CD25−CD45RBhigh T cells differentiated into a greater number of Tregs within the recipient mice, resulting in attenuated symptoms of colitis." (PMID 40757098, 2025). "To comprehensively assess mucosal T cell responses in DSS-induced colitis, we profiled major CD4+ T cell subsets—Th1, Th2, Th17, and Treg—by evaluating lineage-defining transcription factors and signature cytokines at both the mRNA and cellular levels." (PMID 41023976, 2025). "Naïve CD4+ T cells previously stimulated in the presence or absence of IL-36γ, from wild type (WT) or IFNγ-/- mice were transferred to Rag-/- mice to induce colitis." (PMID 40642091, 2025). "PDK4 deletion in CD4+ T cells attenuates colitis through metabolic regulation, underscoring the need for comprehensive investigation of PDK2’s immunometabolic role in IBD." (PMID 40821793, 2025). "CREB deficient Tregs were highly suppressive in vitro and prevented disease activity in a CD4 T cell mediated transfer colitis in an IL-10 dependent way." (PMID 40777015, 2025).
colitis (continued). "Our previous work also demonstrated that peroral administration of L. reuteri reduces pro-inflammatory CD11b+CD11c+ DCs in mesenteric lymph nodes (MLNs), key sources of inflammatory cytokines—while expanding Foxp3+CD4+ T cells during colitis." (PMID 40298818, 2025). "This suggested potential application of CD4 Immuno-PET imaging in monitoring colitis induced by immune checkpoint inhibitors." (PMID 40265075, 2025). "In such chronically lymphopenic environment naive CD4+ T cells robustly proliferate to trigger colitis through fast homeostatic proliferation." (PMID 40303402, 2025). "PET/CT imaging revealed increased uptake of CD4+ T cells in the colon, caecum, and mesenteric lymph nodes of the mice with colitis." (PMID 39747850, 2025). "Since the activation of T cells is a critical step in their differentiation process, we analyzed the activation status of CD4+ T cells in DSS-induced colitis by flow cytometry." (PMID 40422192, 2025). "WT colitis mice also exhibited reduced CD4+ T cell frequencies in IELs, although this was partially restored with sulfasalazine treatment." (PMID 40977735, 2025). "Atg7ΔCD4 mice exhibited exacerbated result of 2,4,6‐trinitrobenzenesulphonic acid‐induced experimental colitis, as did Rag1−/− mice adoptively transferred with CD45RBhigh CD4+ T cells from Atg7ΔCD4 donors." (PMID 40887825, 2025). "In the context of intestinal inflammation, high glucose intake has been reported to induce overactivation of CD4+ T cells and exaggeration of colitis." (PMID 40303402, 2025). "To further characterize how PD-L1/miR-27a-3p-enriched EVs modulate CD4+ T-cell responses, we performed single-cell RNA sequencing (scRNA-seq) on splenic CD4+ T cells isolated from humanized mice models of colitis treated with either PBS or dual-targeting EVs." (PMID 41444211, 2025). "We previously demonstrated that the accumulated CD4+ TH17 cells in colon tissues are critical to protect Tak1ΔM/ΔM mice against colitis and CRC." (PMID 40749055, 2025). "Transfer of regulatory T cells (CD4+ CD25+ CD45RBlow) also improved inflammation in mice with colitis." (PMID 40649879, 2025). "Our results demonstrate that stimulating naïve CD4+ T cells with IL-36γ significantly induced cell expansion in vitro and colitis in vivo." (PMID 40642091, 2025). "Plasma GLP-1 is also elevated in mice with colitis induced by adoptive transfer of CD4+CD25– T cells, suggesting that a compromised intestinal barrier and translocation of intestinal microbes promote GLP-1 release." (PMID 41178710, 2025). "They showed that mice bearing a deletion of CREB in all CD4+ T cells prevented T cell-mediated transfer colitis comparable to our model." (PMID 40777015, 2025). "According to a 2023 study, oral administration of PELNs effectively alleviates acute colitis by promoting the expansion of CD4+CD8+ T cells." (PMID 41471741, 2025). "Using a CD4+ T cell transfer-mediated colitis model, a study demonstrated that Themis regulates CD4+ T cell effector function by controlling NFAT nuclear translocation and metabolic reprogramming." (PMID 40777021, 2025). "We commenced by isolating naïve CD4+ T cells from both WT and Nat10 cKO mice, and then transferred them separately into Rag1−/− recipient mice, thereby inducing an adoptive transfer colitis model." (PMID 40038243, 2025). "In our study, we found that Atg7 deletion in CD4+ T cells aggravated colitis, suggesting the ATG7 functions as protective factor in T cell‐mediated immune regulation." (PMID 40887825, 2025). "Seemingly paradoxically, complete STING deficiency or cell-specific STING deletion in splenic CD4 T cells increases the severity of colitis in DSS-induced colitis models." (PMID 40621423, 2025). "In an adoptive transfer model of colitis, SHP2‐deficient CD4+CD25−CD45RBhigh T cells exhibited reduced pathogenicity and increased Treg generation compared to wild‐type cells." (PMID 40757098, 2025).
colitis (continued). "Most importantly, the CD4+Notch2+Foxp3lo T cells in the colitis model mice also expressed membrane−bound TNFα and TGF−β (LAP)." (PMID 40702356, 2025). "TF+CD3+CD4+ T cells are present in both the colons of mice with experimental colitis and blood and colonic tissue from patients with IBD." (PMID 39956825, 2025). "In IELs, WT colitis mice exhibited a significant reduction in CD4+, CD8+, NK1.1+, and CD8+NK1.1+ cells compared to WT control mice." (PMID 40977735, 2025). "It is known that increased IFN-γ production after adoptive transfer of naïve CD4+ T cells into Rag2−/− mice contributes to the development of colitis." (PMID 40680114, 2025). "We show that TF expression is upregulated in the intestinal tissue of IBD patients and mice with colitis, and we report the elevated presence of CD4+TF+ T cells in the gut mucosa during colitis and in the circulation of IBD patients." (PMID 39956825, 2025). "Using in vitro assays, humanized colitis models, and transcriptomic analyses including single-cell RNA sequencing, we demonstrated that these engineered EVs reprogram inflammatory CD4+ T cells, suppress effector polarization, and enhance FOXP3+ Treg subsets." (PMID 41444211, 2025). "Wu and colleagues developed a radiolabelled anti-mouse CD4 cys-diabody (89Zr-malDFO-GK1.5 cDb) for imaging CD4+ T cells in a mouse model of colitis." (PMID 40265075, 2025). "In a mouse model of colitis, the Hobit- Blimp-1- CD4+ TRM cells lead to reduced chemokines expression, impaired leukocyte recruitment, and decreased expression of proinflammatory molecules." (PMID 40124381, 2025). "In experimental models, the transfer of Treg-enriched cells has been shown to prevent colitis, and transferring CD4+CD25+ Tregs reduces established colitis, demonstrating their anti-inflammatory action." (PMID 40429917, 2025). "In this study, we observed that both CCR2+GMSCs and GMSCs notably decreased IFN-γ or IL-17 secreting CD4+T lymphocytes when compared with untreated colitis rats." (PMID 40472038, 2025). "Overall, these findings demonstrate that the IL-12/IL-12R signaling pathway plays a central role in mediating the pathogenesis of colitis by regulating the effector functions of mucosal CD4+ T cells." (PMID 38498592, 2024). "We found that colonic lamina propria CD4+ T cells from colitis mice showed 532 DEG compared with healthy controls." (PMID 38719901, 2024). "We focused on effector CD4+ T cells due to their central role in the development of intestinal inflammation in the colitis transfer model." (PMID 38719901, 2024). "This suggests that CD4+ T cells are the primary cellular targets for the immunomodulatory effects of IL-12 signaling during colitis." (PMID 38498592, 2024). "We generated and used mice devoid of IF1 in T lymphocytes and a DSS model of colon inflammation to illustrate that IF1-knockout mice cannot mount an effective CD4+ immune response against bacterial infection what compromises their survival." (PMID 38799559, 2024). "This colitis model uses a transfer of CD4+CD45RBhi T cells (naïve T cells) into Rag1−/− mice to induce intestinal disease." (PMID 38363052, 2024). "Core fucosylation has been identified as a potential therapeutic target for inflammatory bowel disease, and decreased core fucosylation in CD4+ T cells has shown a protective effect on the course of T cell-mediated colitis." (PMID 38911244, 2024). "Activated T cells, macrophages, and neutrophils are positively associated with the inflammation that accompanies IBD pathogenesis, and colitis is characterized by a higher influx of activated CD4 T cells and Th17 cells." (PMID 39255739, 2024). "We determined the frequencies of Tregs (CD4+FOXP3+), Th1 cells (CD4+CXCR3+), and Tfh cells (CD4+CXCR5+) in the colonic lamina propria in DSS-induced colitis." (PMID 38396052, 2024).